P4HA1 (prolyl 4-hydroxylase subunit alpha 1)
Diseases named in the same sentence as P4HA1 in open-access papers (continued):
Sharing a sentence is not in itself a finding about the gene and the disease.
Stroke (1 paper, 2024). Sudden impairment of blood flow to a part of the brain due to occlusion or rupture of an artery to the brain. "We found two stages of microglia from sham- to stroke-based on the pseudo-time analysis and the risk gene: P4ha1 has a critical role in the stage transition." (PMID 39021802, 2024). "TLR5 and P4HA1 are positively associated with glycolysis in both diseases; while BEX2 is negatively associated with glycolysis in both stroke and MS." (PMID 39021802, 2024). "First, we found several metabolic pathways shared in two diseases and BEX2 is negatively associated with glycolysis in both stroke and MS, while TLR5 and P4HA1 are positively associated with glycolysis in stroke and MS." (PMID 39021802, 2024).
tendinopathies (1 paper, 2015). "We suggest that these three insults, inhibition of prolyl and lysyl dioxygenases, reduction of P4HA1 and LH1 mRNA levels, and reduced tendon vascularization upon HIF-1α depletion, together account for FQ-induced tendinopathies." (PMID 26205818, 2015).
cancer (78 papers, 2014 to 2025). A tumor composed of atypical neoplastic, often pleomorphic cells that invade other tissues. "P4HA1, a key enzyme involved in collagen biosynthesis, has been previously implicated in various cancers." (PMID 41469036, 2025). "This unique subcluster exhibited concurrent activation of stem cell development and inflammatory response pathways, suggesting the role of P4HA1 in regulating these biological processes linked to cancer initiation and progression." (PMID 40694594, 2025). "As further studies are being conducted, the potential role of P4HA1 in the development of fibrosis-associated diseases and cancer is becoming clear." (PMID 39568592, 2024). "A pan-cancer study showed that P4HA1 is not only associated with poor prognosis in most tumors, but its overexpression also predicts an immunosuppressive TME." (PMID 37055822, 2023). "For the correlation between P4HA1 and CNA, we discovered that P4HA1 expression was positively correlated with CNA in 18 of 33 tumor types, indicating that elevated CNA was one of the main causes of high P4HA1 expression in pan-cancer." (PMID 34966739, 2021). "KEGG pathways analysis results indicated that P4HA1 implicated in cell cycle, metabolism, pathway in cancer and HIF-1 signaling pathways." (PMID 34659558, 2021). "Proline 4-hydroxylase subunit α-1 (P4HA1) is associated with a variety of malignant tumor development pathways, such as EMT, angiogenesis, invasion, inflammation, tumor metabolism and glycolysis pathways." (PMID 34217310, 2021). "Immunosuppressive cells, like nTreg, iTreg, and TAMs, were positively linked to P4HA1 expression in pan-cancer and LUAD." (PMID 34966739, 2021). "In this work, we carried out a pan-cancer analysis of P4HA1 using online databases to systematically profile P4HA1 expression, genetic alteration, association with immune infiltration and DNA methylation, and relevant cellular pathways across various cancers." (PMID 35812752, 2022). "We also found that high CNA was one of the main causes of high P4HA1 expression in pan-cancer." (PMID 34966739, 2021). "UniCox results indicated that P4HA1 acted as a risk factor for OS in patients with 12 cancer types." (PMID 34966739, 2021). "It has previously been observed that P4HA1 implicated in the tumorigenesis of various cancers." (PMID 34659558, 2021). "Deregulated P4HA1 expression has been also implicated in cancer development and progression." (PMID 32500033, 2020). "Additionally, P4HA1 overexpression in cancer has been linked to tumor progression." (PMID 40332386, 2025). "Additionally, we discovered that P4HA1 expression was positively associated with infiltration levels of immunosuppressive cells, such as tumor-associated macrophages, cancer-associated fibroblasts, nTregs, and iTregs, and negatively correlated with CD8+ T and NK cells in pan-cancer." (PMID 34966739, 2021). "The P4HA1 9a isoform renders enhanced invasive potential to cancer cells as it augments invasion conducive ECM by increasing deposition of collagen." (PMID 40016181, 2025). "Beyond its structural role, P4HA1 plays a critical function in modulating the tumor microenvironment by influencing extracellular matrix remodeling, thereby facilitating cancer cell invasion and metastasis." (PMID 41080752, 2025). "Other studies have also interrogated the mechanism by which P4HA1 regulates cancer invasion in other tumor types, identifying EMT and matrix metalloproteinase activity as potential downstream mediators." (PMID 40332386, 2025). "For example, in breast cancer, P4HA1 can contribute to chemoresistance by controlling cancer cell stemness in a hypoxia-inducible factor (HIF)–dependent manner." (PMID 40332386, 2025). "Our results indicate that inhibiting P4HA1 not only directly impacts cancer cells but also modulates the immune landscape by reducing TAM infiltration." (PMID 41469036, 2025).
cancer (continued). "We showed that CAF-CM and LA-stimulated PCa cells increase the transendothelial migration ability of cancer cells, and this increase was impaired by P4HA1 genetic depletion." (PMID 38907027, 2024). "We reviewed the possible strategies of P4HA1 in the diagnosis and treatment of fibrosis-related diseases and cancers, and analyzed its potential relevance as a biomarker in the diagnosis and treatment of fibrosis-related diseases and cancer." (PMID 39568592, 2024). "Overall, research on the role of screening small-molecule drugs targeting P4HA1 in organ fibrosis diseases and cancer is limited." (PMID 39568592, 2024). "Collagen can promote the invasion and migration of malignant tumors, and P4HA1 is a key enzyme of collagen." (PMID 39568592, 2024). "P4HA1 and other ECM-related enzymes have been associated to higher tumor aggressiveness in different cancer models and its expression is transcriptionally controlled by HIF-1." (PMID 38907027, 2024). "Collectively, these results suggest that the lactate-sustained P4HA1/DDR1 axis contributes to the cancer cell colonization and the formation of metastasis in vivo." (PMID 38907027, 2024). "Bioinformatics analysis has identified P4HA1 as a glycolysis-related gene in various cancers, suggesting its potential involvement in glycolysis-induced angiogenesis." (PMID 38238754, 2024). "Given the fundamental role of glycolysis in angiogenesis, and previous bioinformatics analyses linking P4HA1 to glycolysis in cancers, we conducted RNA-seq analysis to investigate the underlying mechanism of P4HA1-induced angiogenesis." (PMID 38238754, 2024). "P4HA1 expression was correlated with infiltration levels of immunosuppressive cells in most cancer types." (PMID 36999961, 2023). "To determine the prognostic value of P4HA1 expression across cancer types, we divided the tumors into high-expression and low-expression cohorts based on the median expression of P4HA1 and analyzed its relationship with survival in the TCGA and GEO databases." (PMID 35812752, 2022). "Although we performed a pan-cancer analysis of P4HA1 examining several aspects, there are still limitations to this study." (PMID 35812752, 2022). "Emerging evidence has revealed that P4HA1 participates in the initiation and development of several malignant tumors." (PMID 35812752, 2022). "P4HA1 expression was remarkedly correlated with the infiltrating immune cells in most cancers (top three cancers: CESC, clear cell RCC, and LGG)." (PMID 35812752, 2022). "The associations of P4HA1 expression with LAG3, ICOS, CTLA4, CD48, TNFSF14, and CD27 expression were inconsistent among cancer types." (PMID 35812752, 2022). "The EPIC algorithms, TIMER, MCPCOUNTER, XCELL, TIDE, TIMER, CIBERSORT, CIBERSORT-ABS, and QUANTISEQ, were used to evaluate the correlation of CAF and CD8+ T cell infiltration with P4HA1 gene expression in various cancers." (PMID 35812752, 2022). "Genomic and epigenetic alterations of P4HA1 and the correlation of P4HA1 with DNA methylation in different cancers were also analyzed across multiple databases." (PMID 35812752, 2022). "In this paper, we conducted a comprehensive bioinformatics analysis of P4HA1 function in pan-cancer and identified P4HA1 as a potential prognostic biomarker and therapeutic target of pan-cancer." (PMID 34966739, 2021). "GSEA results displayed that P4HA1 participated in immune regulation-related pathways in pan-cancer such as cytokine signaling in immune system, innate immune system, and adaptive immune system." (PMID 34966739, 2021). "Prolyl 4-hydroxylase subunit alpha 1 (P4HA1) is the core active catalytic portion of prolyl 4-hydroxylase, and has contributed to tumorigenesis in several cancers." (PMID 34659558, 2021). "To explore the possible pathway of P4HA1 involved in pan-cancer, we conducted GSEA based on Reactome pathway database." (PMID 34966739, 2021). "Our study assessed P4HA1 expression and discovered elevated P4HA1 expression in 26 of 33 cancer types." (PMID 34966739, 2021).
cancer (continued). "As a result, this study investigated the role of P4HA1 in pan-cancer and its impact on tumor microenvironment using bioinformatics analysis." (PMID 34966739, 2021). "This study comprehensively analyzed the role of P4HA1 using multi-omics data from TCGA database for 33 cancers, including expression, clinical features, prognostic values, DNA methylation, copy number alteration (CNA), and mutation status of P4HA1." (PMID 34966739, 2021). "Together with our study, all these studies demonstrated that P4HA1 was a potential biomarker for diagnosis and prognosis in pan-cancer." (PMID 34966739, 2021). "GSEA results suggested that P4HA1 was mainly involved in cell cycle and immune-related pathways in pan-cancer." (PMID 34966739, 2021). "This study aimed to evaluate the prognostic value of P4HA1 in pan-cancer and explore the relationship between P4HA1 expression and TIME." (PMID 34966739, 2021). "We found that infiltration levels of immunosuppressive cells, such as TAMs, nTregs, and iTregs, were positively correlated with P4HA1 expression in pan-cancer." (PMID 34966739, 2021). "Kaplan-Meier OS analysis revealed that increased P4HA1 expression indicated worse survival of patients with 18 cancer types." (PMID 34966739, 2021). "Comparing tumors and adjacent normal tissues in TCGA cohort, we also observed that P4HA1 was overexpressed in 12 cancers." (PMID 34966739, 2021). "Prolyl 4‐hydroxylase subunit alpha 1 (P4HA1) plays a critical role in modulating the extracellular matrix and promoting tumor progression in various cancers." (PMID 31782831, 2020). "Silence of P4HA1 is sufficient to inhibit cancer metastasis and sensitize cancer cells to chemotherapeutic agents." (PMID 32927660, 2020). "The highest glycolysis score, LDHA and PGK1 mRNA abundance were observed under high hypoxia and high P4HA1 expression in some cancer types." (PMID 32635458, 2020). "In HNSCC, P4HA1 coexpressed genes were additionally enriched in some cancer‐related and metabolism‐related pathways, such as HIF‐1 signaling pathway, lysine degradation pathway, and gluconeogenesis pathway." (PMID 31782831, 2020). "The results showed that P4HA1 was correlated with PGK1 (r = 0.16~0.81) in 25 cancer types and correlated with LDHA (r = 0.13~0.79) in 24 cancer types (p < 0.05)." (PMID 32635458, 2020). "The different expression of HSPA8 and P4HA1 was observed in cancer cell lines and tumor fragments of multiple cancer types under hypoxia compared with normoxic conditions from previous studies (GEO numbers see Methods)." (PMID 32635458, 2020). "The authors show that P4HA1 promotes HIF1α-dependent cancer stemness and chemoresistance by reducing the availability of α-KG, and support the idea that P4H is a promising target to inhibit tumor progression and sensitize TNBC to chemotherapy." (PMID 32500033, 2020). "GSEA showed that several cancer-related and immune-related signaling pathways exhibited prominently differential enrichment in P4HA1-high expression phenotype." (PMID 33299876, 2020). "The overall expression profile of P4HA1 in various cancers was first analyzed using the Oncomine database by making comparisons between cancer and normal tissue samples." (PMID 33415167, 2020). "Previous research reported increased levels of P4HA2 and P4HA1 (the two isomers of collagen prolyl 4-hydroxylase) in several types of human cancers and that both enzymes promoted glycolysis in tumor cells." (PMID 33194424, 2020). "Meanwhile, upregulation of P4HA1 has been validated to facilitate carcinogenesis and progression of several cancers." (PMID 33299876, 2020). "P4HA1 was up regulated in cancer cells cultured with hypoxia across all single datasets (p < 0.05), however, HSPA8 was showed the opposite trend in the same conditions in five datasets (p < 0.05)." (PMID 32635458, 2020). "Afterwards, TCGA and GTEx data were used to analyze the expression of P4HA1 in pan-cancer, in order to further quantitatively verify its expression in various tumors." (PMID 33415167, 2020).
cancer (continued). "P4HA1 mRNA and protein expression in cancer and normal tissues were analyzed using The Cancer Genome Atlas (TCGA), Gene Expression Omnibus, and Human Protein Atlas databases." (PMID 31782831, 2020). "Recently, studies showed that expression of P4HA1, 2 and 3 is induced during cancer development and progression, and that increased P4HA expression correlates with poor prognosis in cancer patient." (PMID 31225497, 2019). "We also found that P4HA1 protein levels were increased in TNBC cell lines compared to luminal cancer cells." (PMID 30367042, 2018). "We also found that expression of the HIF-1α PPAA mutant restored tumorsphere formation in P4HA1-silenced cancer cells." (PMID 30367042, 2018). "We also observed altered expression of Matrix metalloproteases (MMP1 and MMP2) and Fibronectin leucine rich transmembrane protein 3 (FLRT3) upon P4HA1 perturbation in cancer cells." (PMID 25115393, 2014). "High expression of P4HA1 negatively correlated with survival in many cancer types." (PMID 39966387, 2025). "Furthermore, P4HA1 can promote resistance to chemotherapy by regulating the HIF-1α-dependent cancer cell stemness." (PMID 40379610, 2025). "Our results suggest that the P4HA1 gene plays an important role in pathways related to stem cell development and inflammation, which are essential for both tissue morphogenesis and repair, as well as cancer progression." (PMID 40694594, 2025). "This raises the possibility of a common thread linking P4HA1 to invasion across diverse malignancies and suggests that targeting P4HA1 may hold promise across multiple cancer types." (PMID 40332386, 2025). "The contribution of P4HA1 in tumor progression concerns the ability to stimulate migration, invasion and angiogenesis and to support cancer cell dedifferentiation during tumoral progression, when aggressive tumors develop following epithelial-mesenchymal transition activation." (PMID 39828692, 2025). "Our work provides new insights into how P4HA1 might serve as a key regulator of mammary gland development and a potential target to slow down or prevent the progression of aggressive cancers." (PMID 40694594, 2025). "P4HA1 promotes chemoresistance by regulating HIF-1-dependent cancer cell lineage." (PMID 38544822, 2024). "In addition, to further determine the role of P4HA1 during cancer progression, we performed a correlation experiment using lentivirus-mediated knockdown systems in 5-8F cells." (PMID 38806556, 2024). "Consequently, we conducted a systematic review and discussion on the role of P4HA1 in the pathogenesis of various fibrosis-related diseases and cancers." (PMID 39568592, 2024). "The literature has confirmed that P4HA1 expression is increased in many types of cancer." (PMID 37377864, 2023). "Overall, these findings significantly proved that P4HA1 could function as a potential prognostic biomarker in multiple cancer types." (PMID 35812752, 2022). "Our comprehensive pan-cancer analysis suggested that P4HA1 might be a latent prognostic biomarker for clinical diagnosis and assessment of cancers." (PMID 35812752, 2022). "Overall, these results have proven that P4HA1 is correlated with tumor immunity, which might explain its influence on the prognosis and survival of cancer patients." (PMID 35812752, 2022). "In addition, the ability of P4HA1 expression to predict prognosis in different cancer types was analyzed to investigate its potential therapeutic utility." (PMID 35812752, 2022). "Additionally, in PDAC, P4HA1 knockdown significantly inhibited cancer cell proliferation, attenuated the expression of cancer stem cell markers, and increased the susceptibility of PDAC cell lines to gemcitabine." (PMID 35804902, 2022). "However, P4HA1 has also recently been revealed to be involved in the carcinogenesis of different types of cancers." (PMID 35812752, 2022).